TNF (tumor necrosis factor)
Diseases named in the same sentence as TNF in open-access papers (continued):
Sharing a sentence is not in itself a finding about the gene and the disease.
Sepsis (continued). "In the present study, salidroside treatment reversed both sepsis-induced downregulation of SIRT1 expression and increased proinflammatory cytokines (TNF-α and IL-6) secretion." (PMID 28931916, 2017). "We observed that subjects with late onset of sepsis (LOS), as well as those with early onset of sepsis (EOS), had a substantial increase in serum TNF-α." (PMID 28367457, 2017). "Induction of sepsis by CLP resulted in early 1.5–20-fold increases in IL-6, IL-10, IFNγ and TNFα over that induced by sham surgery." (PMID 28724977, 2017). "Spermine inhibits the production of IL-12, TNF-α, IL-1, IL-6, MIP-1a, and MIP-1b by in vitro-stimulated macrophages and protects against lethal sepsis by attenuating local and systemic inflammatory response." (PMID 29137411, 2017). "Herein, sepsis induction reactivated long-lived T. gondii-experienced T cells to produce IFN-γ and TNF-α in both the mesenteric lymph nodes and peritoneum." (PMID 28439500, 2017). "Whole blood was stimulated with LPS and both TNFα and HLA-DR using FACS were measured in sepsis patients." (PMID 28771573, 2017). "CLP promoted significantly high expression of pro-inflammatory cytokine TNF-α (3-fold) and IFN-γ (2.5-fold) compared with sham control (set at 1-fold) on day 12 after sepsis." (PMID 28525390, 2017). "As shown in this study cohort, the median IL10/TNF ratio was lowest among SIRS-N patients at 1.2 and increased progressively with increasing severity of sepsis to 4.5 among those with septic shock." (PMID 31058274, 2017). "We found that the inflammation indicators, NF-κB, MMP-9, RANTES, and TNF-α, along with oxidative stress and mitochondrial damage, were upregulated by ARDS with sepsis in animals." (PMID 29137274, 2017). "MMP-8 was upregulated in LPS-stimulated microglia and in the brains of mice with sepsis, and treatment with an MMP-8 inhibitor (M8I) dramatically suppressed the secretion of proinflammatory molecules, particularly TNF-α." (PMID 29108257, 2017). "The concentration of inflammatory cytokines (TNF-a, IL-6, MCP-1 and IL-10) were dramatically increased in plasma and peritoneum in mice under sepsis." (PMID 28273909, 2017). "Salidroside reduced the production of pro-inflammatory cytokines (TNF-α and IL-6) through a SIRT1-mediated inhibition of NF-κB activation pathway in the early sepsis phase." (PMID 28931916, 2017). "Since the lipopolysaccharide (LPS) from the cell wall of γ-negative bacteria like E. coli causes sepsis by inducing pro-inflammatory mediators including TNF-α and IL-6, this study detected whether MS19 could reduce the production of these inflammatory cytokines." (PMID 28492513, 2017). "The initially elevated IL10/TNF ratio normalized to <1 for both SIRS-N and SIRS-P (sepsis and severe sepsis) patients following 72 h of effective therapy while those with septic shock remained elevated at 1.9." (PMID 31058274, 2017). "Sepsis serum supplemented with EGF 5 ng/ml and TNF-α in all concentrations improved keratinocyte migration." (PMID 28086962, 2017). "Activation of NLRs and RLRs promote the assembly of inflammasomes 14 which mediate the release of inflammatory cytokines including TNF‐α, IL‐1, IL‐6, IL‐18, and HMGB1, which itself also possesses an inflammatory cytokine function in sepsis." (PMID 28186706, 2017). "Systemic LPS injection results in a strong and immediate increase of several pro-inflammatory cytokines such as IL-6, TNF and IL-1β compared to a prolonged cytokine increase after CLP which resembles the progression and characteristics of human sepsis." (PMID 27437704, 2016). "PDF can effectively eliminate more large pivotal inflammatory mediators of TNFα and HMGB1 and improve the sepsis-related gut barrier dysfunction and apoptosis of lymphocyte, and meanwhile, it benefits the circulation function and prolong the survival time." (PMID 27682607, 2016).
Sepsis (continued). "While serving as an important inflammatory mediator, tumor necrosis factor alpha (TNF-α) can induce many detrimental effects in a broad range of diseases, such as sepsis, cancer, and autoimmune disorders." (PMID 27406560, 2016). "The rapid peaks in TNF-α and IL-10 are supported by data published for Wingate SIT and are more akin to the release pattern seen during sepsis." (PMID 27034919, 2016). "The proinflammatory cytokines (TNF-α, IFN-γ, and IL-6) increase differentially in neonates with sepsis based on gestational age." (PMID 27293317, 2016). "It is very gratifying to see that PDF effectively attenuated the TNF-α and HMGB1 levels in serum and also improved apoptosis of lymphocyte and sepsis-related gut barrier injury." (PMID 27682607, 2016). "In the current study, we pursued further aspects of WISP1 modulation of TLR signaling in lungs of mice after sepsis and TLR4 mediated release of TNF-α in macrophages." (PMID 27349568, 2016). "In accordance with this observation, MFG-E8 suppressed inflammation in sepsis and ischemia/reperfusion conditions with LPS-TLR4 signaling by reducing the production of proinflammatory cytokines such as TNF-α, IL-1β, and IL-6." (PMID 27429513, 2016). "In a murine sepsis model, lncRNA-HOTAIR appeared to modulate TNF-α production in cardiomyocytes via the nuclear factor (NF)-κB pathway." (PMID 27890015, 2016). "Inflammatory cytokines (TNF-α, HMGB1, IL-1β, IL-6, and IL-8) were increased while anti-inflammatory cytokines (IL-10) were decreased, in serum and lung in sepsis patients." (PMID 27413421, 2016). "The proinflammatory cytokines IFN-γ, TNF-α, and IL-6 were elevated in 9/11 PT infants with sepsis but only in 1/12 VPT infants with sepsis (P < 0.05, χ2 test), resulting in 10/23 infants with sepsis identified." (PMID 27293317, 2016). "The amounts of TNF in supernatants from BCG-stimulated PBMCs were significantly (p = 0.02 and p = 0.03, respectively) lower in the patients with severe sepsis (54 pg/ml) than in the healthy controls (295 pg/ml) and the patients with cured Q fever (362 pg/ml)." (PMID 27441846, 2016). "The administration of IDC-derived exosome containing MFG-E8 significantly suppressed the expression of proinflammatory cytokines, including TNF-α, IL-6, and High Mobility Group Box 1 (HMGB1), in CLP sepsis animals." (PMID 27429513, 2016). "Among the sepsis patients, plasma NT-proBNP levels positively correlated with CRP (r = 0.544), procalcitonin (r = 0.815), TNF-α (r = 0.712), and IL6 (r = 0.682; P < 0.001 for all)." (PMID 26812689, 2016). "al., the cytokine secretions of TNF-α, IFN-γ, IL-6 and IL-10 were globally decreased after LPS and α-CD3/28 stimulation in patients who died from sepsis." (PMID 27056672, 2016). "Similar to the serum results, the concentration of IL-6, TNF-α, IL-1β and IL-1α in the colonic wall rose significantly following CLP-induced sepsis." (PMID 27044016, 2016). "It was suggested that various miRNAs directly target the tumor necrosis factor (TNF) pathway, a major regulator of pro-inflammatory processes in sepsis." (PMID 26761003, 2016). "Here, we demonstrate that methane-rich saline (MS) treatment can protect mice from LPS-induced endotoxin shock, bacteria-induced sepsis and DSS-induced colitis by suppressing TNF-α and IL-6 production." (PMID 27405597, 2016). "Inflammatory cytokines like TNF-α and HMGB1 were increased, while anti-inflammatory cytokines like IL-10 were decreased in sepsis." (PMID 27413421, 2016). "Inflammatory cytokines (TNF-α, IL-6, and HMGB1) were increased, while anti-inflammatory cytokines (IL-10) were decreased in sepsis." (PMID 27413421, 2016). "In light of the notion that IL-6 and TNF-α promote wound healing and tissue repair, increased production of these cytokines may also limit pathogens from penetrating the epithelial lining of the intestine and invading into the peritoneal cavity to induce sepsis, an extreme case of IBD." (PMID 26439699, 2015).
Sepsis (continued). "The significant increase in CK, LDH, TNF-α and IL-6 levels in the culture supernatant indicated that the H9C2 cell model of sepsis had been successfully constructed." (PMID 25873251, 2015). "We found that the severe sepsis patients expressed significantly higher levels of CX3CL1, IL-6R, and TNF-a than the healthy controls." (PMID 25888255, 2015). "In our study, pro-inflammatory cytokines (TNF-α and IL-1β) and WBC count were detected for the evaluation of the severity of sepsis in each group." (PMID 26149595, 2015). "The differences in the expression levels of ADAM10 substrates (CX3CL1, IL-6R and TNF-a) and the pro-inflammatory cytokines IL-1ß and IL-6 according to the ADAM10 genotype were analyzed in PBMCs from the sepsis patients and the controls." (PMID 25888255, 2015). "When sepsis was induced in rat pretreated with CAPE (group 3), TNF-alpha levels were found to be similar to group 1 (P > 0.05) and significantly lower compared to group 2 (P = 0.039)." (PMID 25948886, 2015). "The significant increase in the levels of CK, LDH, TNF-α and IL-6 in our study indicated that the H9C2 cell model of sepsis had been created successfully." (PMID 25873251, 2015). "In summary, this study demonstrated that CLP-induced sepsis promoted the expression of TLR4 and Myd88 and the activation of ERK1/2 and NF-κB in lung tissue, and ultimately induced the generation of TNF-α and IL-6 in BALF and plasma." (PMID 25929655, 2015). "Our results showed that rhein treatment decreased the level of TNF-α and IL-1β in the two sepsis models in vivo, which suggest that the protection of rhein against septic-AKI are related to down regulation of TNF-α and IL-1β level." (PMID 26149595, 2015). "It has been previously shown that Gln directly induces LPS-stimulated macrophages' TNF-α and macrophages' HSP72 expression, while, at the same time, it inhibits peritoneal macrophages' TNF-α in murine sepsis." (PMID 26550577, 2015). "Overall, results revealed that pretreatment with CAPE significantly reduced serum ET-1, TNF-alpha, and MDA levels while increasing SOD activities, when sepsis was induced in a rat sepsis model." (PMID 25948886, 2015). "Xia and colleagues have shown that Ash1l, a H3K4 methyltransferase, suppressed interleukin-6 (IL-6), and tumor necrosis factor (TNF) production in toll-like receptor (TLR)-triggered macrophages, protecting mice from sepsis." (PMID 26834738, 2015). "Endotoxin mediated septicemia often involve excessive inflammation mediated by several inflammatory genes including COX-2, TNF-α, IL-12 and IL-6." (PMID 25428720, 2014). "To link our findings showing TNF-α signaling and complement activation contribute to WNV-induced disease and sepsis, we assessed complement activation in WNV-infected CD11c-Cre+Ifnarf/f mice treated with blocking anti-TNF-α MAbs." (PMID 24743949, 2014). "The strengths of our study were the large sample size and the follow-up of circulating TIMP-1, MMP-9, TNF-alpha, IL-10, and PAI-1 levels throughout the first week after diagnosis of severe sepsis." (PMID 24727739, 2014). "In a study by our group using an LPS-induced DIC model (sepsis DIC model), the administration of immunoglobulin inhibited the inflammatory cytokines TNF and interleukin-6 (IL-6), and coagulation and pathological thrombus formation were suppressed." (PMID 25520834, 2014). "Blood samples were collected at the time that severe sepsis was diagnosed to determine serum levels of CCCK-18, tumor necrosis factor (TNF)-alpha, interleukin (IL)-6 and IL-10." (PMID 25290885, 2014). "APN deficiency elicits the production of inflammatory mediators, including TNF-α, IL-6 and monocyte chemoattractant protein (MCP)-1 and aggravates sepsis-induced hepatic injury." (PMID 27602369, 2014). "Administration of rosiglitazone, which increased the plasma APN concentration, significantly lowered plasma levels of inflammatory mediators, including TNF-α, IL-6, and MCP-1 during sepsis." (PMID 27602369, 2014).
Sepsis (continued). "As a result, overstimulated macrophages release large amounts of TNF-alpha, IL-1, and IL-6, which lead to the systemic inflammatory response syndrome (SIRS), sepsis, multiple organ failure, and/or death." (PMID 24511409, 2014). "The findings reported in the present study indicate that EA induces an anti-inflammatory mechanism that reduces TNF, IL-6, nitrite, and HMGB1 production in one of the more widely used rat models for studying polymicrobial sepsis." (PMID 25057275, 2014). "This cytokine gene expression index consisted of the difference in log mRNA copy numbers for cytokines that were decreased in sepsis, namely, IFNγ, TNFα, IL7, and IL23, and the cytokine increased in sepsis, namely, IL10 (IFNγ + TNFα + IL7 + IL23–IL10)." (PMID 23935244, 2013). "To verify sepsis after CLP procedure we measured IL-6 and TNF-α level in the serum as a marker for the systemic inflammation in septic and non-septic mice on the day of sacrifice." (PMID 24086305, 2013). "To confirm if suppressing inflammatory responses in sepsis by CORM-2 was partly through interruption of the cycle of inflammatory events, we investigated the expression of inflammatory cytokines TNF-α and IL-6 in serum of the septic mice." (PMID 24116078, 2013). "TNF-α, PCT and soluble Trem-1 (sTREM) values were significantly higher (p < 0.05) in patients with severe sepsis compared to simple sepsis." (PMID 23414215, 2013). "The fish oil supplemented diet resulted in increased mortality during infection due to sepsis evident by the presence of serum LPS binding protein (LBP), IL-15 and TNF-α." (PMID 23405155, 2013). "Overproduction of proinflammatory cytokines and chemokines (e.g. TNF-α, IL-12, IFN-γ and IL-8) results in sustained sepsis, shock, and even death." (PMID 24391778, 2013). "It has been shown that systemic proinflammatory cytokines have a central role in sepsis; we investigated next the effects of PD on CLP-induced systemic TNF-α and IL-6 production." (PMID 23431240, 2013). "In a multivariate nominal logistic regression model comparing gene expression in patients with infection and those with sepsis at ICU admission, IL10 (P = 0.02), IFNγ (P < 0.0001), and TNFα (P = 0.03) retained statistical significance." (PMID 23935244, 2013). "On one hand, studies have shown that NE enhances TNF-α secretion from macrophage, whereas others show NE inhibiting TNF-α secretion from splenic macrophages isolated both from a polymicrobial sepsis mouse model and wild type rats." (PMID 23844252, 2013). "An algorithm utilising mRNA copy number for TNFα, IFNγ, IL7, IL10, and IL23 accurately distinguished sepsis from severe sepsis with a receiver operator characteristic value of 0.88." (PMID 23935244, 2013). "In particular, the proinflammatory cytokine TNF-α has been shown to mediate SIRS, ALI, and AKI in animal models of sepsis." (PMID 24265742, 2013). "Cytokine analysis of the inflammatory cytokine tumor necrosis factor alpha (TNF-alpha) demonstrated decreased expression of TNF-alpha in both lung and plasma at 24 hours post CLP induced sepsis." (PMID 24020447, 2013). "Severe sepsis differed from infection by having decreased IL7, IL23, IFNγ, and TNFα gene expression." (PMID 23935244, 2013). "In a rat caecal-ligation model of sepsis, the administration of N/OFQ increased mortality, whereas the N/OFQ antagonist, UFP-101, reduced mortality and decreased TNF-α and other cytokines." (PMID 24124588, 2013). "Anti-PD-L1 antibody administration decreased ALT and AST release in CLP mice, decreased the levels of tumor necrosis factor (TNF)-α, interleukin (IL)-6, and IL-10 mRNA in liver after sepsis challenge." (PMID 24324295, 2013). "Hyporesponsiveness for LPS stimulation was seen in patients with severe sepsis compared to simple sepsis patients for IL6, IL8, IL10 and TNFα reaching significant results for TNFα." (PMID 23414215, 2013).
Sepsis (continued). "When patients with infection and patients with severe sepsis on ICU admission were compared, IL2, IL7, IL23, IFNγ, and TNFα gene expression was lower in patients with sepsis, while IL-27 gene expression was similar in these two groups." (PMID 23935244, 2013). "There is now controversy regarding the role of TNF-α and the SIRS response in the pathophysiology of organ injury after sepsis and the role of animal models used to study sepsis has been questioned." (PMID 24265742, 2013). "Tumor necrosis factor (TNF) and TNF receptor superfamily (TNFR)-mediated immune response play an essential role in the pathogenesis of severe sepsis." (PMID 23029405, 2012). "Furthermore, a recent study showed that polymicrobial sepsis greatly induced generation of inflammatory mediators in hearts, and CMs isolated from septic rodents spontaneously secreted cytokines and chemokines (IL-6, TNF-α, IL-1β, MIP-1α, MIP-2, MCP-1, KC, and IL-10) in a time-dependent manner." (PMID 23233853, 2012). "Ten SNPs in TNF, LTA, TNFRSF1A and TNFRSF1B were genotyped in samples of patients with severe sepsis (n = 432), sepsis (n = 384) and healthy controls (n = 624)." (PMID 23029405, 2012). "The main inflammatory mediators that contribute to myocardial depression in sepsis include interleukins (IL-2, IL-4, IL-6, IL-8, and IL-10), gamma interferon (IFN-γ), TNF-α, IL-1β, and C5a." (PMID 22482045, 2012). "In our study, treatment of myrrh reduced expression of IL-1β, IL-6, and TNF-α in serum and liver during CLP-induced sepsis." (PMID 21826187, 2012). "TNF-α is an important pro-inflammatory cytokine involved in sepsis; several functional SNPs in TNF and LTA have been extensively studied in sepsis." (PMID 23029405, 2012). "In animal models of endotoxemia or sepsis, circulating HMGB1 increases to plateau levels between 24 and 36 h, distinguishing itself from TNF and other early cytokines." (PMID 23193422, 2012). "The up-regulation of TNF-α, IL-1α, IL-1β, CXCL-10, SOCS3, IL-10 at 1 and 2 h in the present study was similar to that observed in blood profiles of sepsis patients at early stages." (PMID 23009705, 2012). "TNF-α is a major mediator of sepsis and endotoxin-induced ALI; after endotoxin infusion in animals, the level of TNF-α peaks in one to two hours in the serum and in eight hours in BALF." (PMID 23078757, 2012). "In particular, rs1800629 (TNF −308) and rs909253 (LTA +252) have been the focus of many investigations on sepsis." (PMID 23029405, 2012). "It has been shown that TNF-α contributes to endothelial barrier breakdown and cytokine transport across the blood-brain barrier (BBB) in sepsis." (PMID 21473788, 2011). "At baseline prior to sepsis induction, PBMC release of TNF-α and IL-8 were 2.1±1.8 and 6.5±2.8 pg/106 cells in response to LPS in the SCD-H group, respectively; in the SCD-C group, the release was 5.1±0.9 and 18.7±8.1, respectively." (PMID 21533222, 2011). "Overproduction of proinflammatory cytokines (e.g. TNF-α, IL-12, IFN-γ and IL-18) results in sustained sepsis, shock, and even death." (PMID 21194488, 2011). "At admission to the ICU, serum NT-proCNP concentrations in the total cohort and the subgroup of sepsis patients were closely correlated to markers of inflammation and bacterial infection, such as PCT, CRP and TNF-α." (PMID 21281508, 2011). "They showed that TNF, IL1-β, CD3D and PRF1 gene expressions were significantly different in patients who developed postoperative sepsis in comparison with patients who recovered uneventfully." (PMID 22027436, 2011). "On the second day of ICU admission, significant elevation of leptin, IL-6 and TNF-α occurred in the SIRS and sepsis groups." (PMID 20230641, 2010). "For example in vivo treatment with nicotine can inhibit TNFα-induced HMGB1 secretion and has a proven therapeutic benefit in models of sepsis." (PMID 20379354, 2010).